Y_RNA (Y RNA )
Gene: Miscellaneous RNA gene on chromosome 14 (67,340,068 to 67,340,176, forward strand). Ensembl gene ENSG00000199755.
Homologues: Orthologues: chimpanzee Y_RNA (98% identical), macaque Y_RNA (94% identical). Paralogues in human: Y_RNA (85% identical), RNY1P11 (83% identical), RNY1 (83% identical), Y_RNA (83% identical), Y_RNA (82% identical), RNY1P10 (81% identical), Y_RNA (81% identical), Y_RNA (80% identical), RNY1P8 (79% identical), Y_RNA (79% identical), Y_RNA (78% identical), Y_RNA (77% identical), and 93 more.